LINC02100 (long independently transcribed non-coding RNA 2100)
Gene: Long non-coding RNA gene on chromosome 5 (18,704,433 to 18,746,208, reverse strand). Ensembl gene ENSG00000248693.
Diseases named in the same sentence as LINC02100 in open-access papers:
LINC02100 is named in the same sentence as 1 disease in open-access papers, as found by Europe PMC text mining. Sharing a sentence is not in itself a finding about the gene and the disease. The quoted sentences say what the papers report.
tumor (1 paper, 2023). "LINC00944, LINC02611, PRKAR1B-AS1, LINC02328 and LINC02100 were expressed at higher levels in ccRCC tumor tissues compared to that in normal tissues, which was consistent with the results of the TCGA-ccRCC cohort." (PMID 37415739, 2023).